INS (insulin)
Diseases named in the same sentence as INS in open-access papers (continued):
Sharing a sentence is not in itself a finding about the gene and the disease.
Obesity (continued). "Increased liver expression of Slc35b4, a Golgi UDP-GlcNAc antiporter, was identified as a quantitative trait locus associated with high-fat diet-induced obesity, insulin resistance and gluconeogenesis in mice." (PMID 26972830, 2016). "We identify striking metabolic sequelae of an R299Q γ2 mutation, including hyperphagia leading to obesity and impaired insulin secretion contributing to glucose intolerance." (PMID 27133129, 2016). "In obese rats and humans it was found that skeletal muscle triglycerides, diacylglycerols, and ceramides cause insulin resistance during obesity through different signaling mechanisms." (PMID 27746742, 2016). "In contrast, the association between obesity, adiponectin and insulin sensitivity is controversial in the cat." (PMID 27136422, 2016). "Obesity is associated with perturbed maternal metabolism, raised plasma hormones, including leptin, insulin, and IGF 1, and the accumulation of inflammatory markers (eg, IL-6)." (PMID 26513002, 2016). "Hyperglycemia is well known risk factor for in addition to other risk factors like male sex, obesity, hypertension, chronic inflammation, resistance to insulin, hypovitaminosis D, and dyslipidemia and some genetic loci and polymorphisms in specific genes." (PMID 28197499, 2016). "Since leptin is closely related to insulin signaling and inflammation, it is considered as a strong risk factor in obesity-related cancer." (PMID 27703473, 2016). "The present study identified specific associations between 10 AAs and the type and degree of obesity, or indices of glucose/insulin regulation, in Japanese adults with preserved glucose metabolism." (PMID 26788116, 2016). "Studies implicate that BAT activation improves insulin sensitivity and is positively associated with resistance of obesity and metabolic diseases." (PMID 26903879, 2016). "A recent meta-analysis concluded that chemerin concentrations in obese subjects and in subjects with metabolic syndrome seem to be associated with obesity and disturbances in lipid, glucose, and insulin metabolism." (PMID 26904119, 2016). "Drosophila studies have provided mechanistic insights into the roles of insulin in cancer risk and progression linked to obesity." (PMID 27604692, 2016). "In adults, there is evidence that intermittent fasting is effective in the short-term (eight weeks to six months) to help individuals with obesity lose body weight (4%–8%) and body fat, and improve insulin sensitivity and other risk factors for T2DM." (PMID 27517953, 2016). "We classify this network into 5 modules and identify new links between the recently discovered fat mass and obesity associated FTO gene with well studied examples such as insulin and leptin." (PMID 26886906, 2016). "Dysregulation of glucose and insulin homeostasis as well as obesity are risk factors for the development of AD." (PMID 27656136, 2016). "Resistin-deficient ob/ob mice show improved glucose tolerance and insulin sensitivity, although they showed increased obesity as well." (PMID 28025491, 2016). "Visceral fat obesity is associated with a reduction of insulin sensitivity and anti-inflammatory cytokines." (PMID 28025491, 2016). "PTP1B-deficient mice are protected from diet-induced obesity through modulation of energy balance, insulin sensitivity, and body fat stores." (PMID 27095436, 2016). "The obesity-associated metabolic syndrome includes hepatic steatosis and altered glucose or insulin sensitivity." (PMID 27456060, 2016). "Obesity is associated with elevations in insulin, free insulin-like growth factors (IGFs), and adipocyte-derived factors that include leptin, TNF-alpha, IL-6, and reductions in adiponectin." (PMID 25811460, 2015). "In both these models, the alteration in tissue fatty acids were associated with improved insulin sensitivity and resistance to diet-induced obesity." (PMID 26679101, 2015). "Since obesity is associated with IR, we next monitored insulin sensitivity in mice fed a HFD for 24, 40, and 52 weeks." (PMID 25979814, 2015).
Obesity (continued). "BCAAs were found to suppress the incidence of hepatocarcinogenesis in patients with HCV-related cirrhosis and obesity that is often associated with IR through modulating insulin signaling." (PMID 26155840, 2015). "PKIA is involved in pancreatic beta-cell function and 16p11.2 has been widely reported in the literature as contributing to the genetic risk of obesity, potentially linked to insulin signalling." (PMID 25424174, 2015). "For example, obesity is associated with increased levels of insulin and free IGF-I, which changes the cellular environment favoring (prostate) cancer development." (PMID 25881129, 2015). "Humans with more copies of the amylase genes AMY1 have higher amylase activity but reduced risk of obesity, in part due to differential starch digestion and potentially increased insulin sensitivity." (PMID 26683458, 2015). "In boys, PAI-1 was associated with obesity, hypertriglyceridemia, insulin secretion, and resistance." (PMID 26633970, 2015). "The results demonstrate that TSP1 deficiency improves metabolic phenotype of HF-fed ApoE-/- mice with reduced obesity-associated systemic inflammation and improved insulin sensitivity." (PMID 25803585, 2015). "LMP7 deficiency conveyed resistant to obesity, and improved glucose intolerance and insulin sensitivity in mice fed with high-fat diet (HFD)." (PMID 26515636, 2015). "A greater postprandial glycemic response to a small meal was positively associated with indicators of a decreased capacity for insulin secretion and negatively associated with obesity." (PMID 25855488, 2015). "Loss of insulin-mediated microvascular recruitment in muscle can alone result in whole body insulin resistance equivalent to that caused by obesity, emphasizing the physiological importance of this process." (PMID 26194188, 2015). "With respect to insulin, obesity is also associated with reduced transport across the BBB, but this is not blocked but rather reversed by triglycerides." (PMID 26041981, 2015). "All measures of obesity were positively associated with indicators of glycaemia and inversely associated with indicators of insulin sensitivity." (PMID 25849815, 2015). "Taken together, in the present study, circulating levels of leptin are found to be associated with well defined cardiovascular risk factors such as obesity, triglycerides, insulin and TNF-α in AMI subjects." (PMID 25762868, 2015). "In conclusion, PAI-1 is associated with obesity, hypertriglyceridemia, insulin secretion, and MetS and suPAR is associated with inflammation in children." (PMID 26633970, 2015). "Obesity, characterized as a state of chronic low-grade inflammation caused by overnutrition, is a major cause of decreased insulin sensitivity, which makes obesity a major risk factor for IR." (PMID 26136779, 2015). "At present, the following three proposed mechanisms exist which aim to explain the association between obesity and aggressive PCa: The insulin/insulin-like growth factor-1 axis, the action of sex hormones and adipokine signaling." (PMID 25663903, 2015). "In male offspring, exercise during pregnancy was able to decrease the metabolic risk conferred by maternal obesity by improving insulin and glucose metabolism." (PMID 25853572, 2015). "Non-alcoholic fatty liver disease (NAFLD) is a common liver disease that is strongly associated with obesity and dysregulation of insulin in the liver." (PMID 26438035, 2015). "Obesity can influence cancer risk by increased production of inflammatory factors, insulin and insulin-like growth factors (IGFs), and altered adipokines, resulting in a state of low-grade chronic inflammation." (PMID 25884832, 2015). "Recently, stearoyl-coenzyme A desaturase-1 (SCD1) down-regulation has been implicated in the prevention of obesity and in the improvement of insulin and leptin sensitivity." (PMID 25871295, 2015).
Obesity (continued). "Lowered circulating levels of androgens in men are associated with insulin resistance and obesity, while testosterone treatment in hypogonadal men improves insulin sensitivity and reduces body fat content." (PMID 26491443, 2015). "For instance, obesity has been shown to influence PC progression in some populations, and is also associated with higher insulin levels and lower testosterone levels." (PMID 26125012, 2015). "In Quebec, gestational diabetes is associated with obesity, fasting insulin levels and raised levels of triglycerides." (PMID 25636170, 2015). "Increased body weight and accumulation of central adiposity lead to changes in leptin and adiponectin levels and reduction of insulin sensitivity; weight loss improves insulin sensitivity and decreases risk for many potential complications of obesity." (PMID 26251693, 2015). "Impaired insulin action in obesity is linked to an excessive fatty acid uptake into insulin sensitive tissues, including skeletal muscle." (PMID 25793412, 2015). "It is the fat that accumulates around the abdominal viscera that is associated with the metabolic complications of obesity, and visceral fat is quantitatively the principal site of adipose tissue inflammation and a major contributor to insulin resistance." (PMID 26516917, 2015). "Genetic mutations or polymorphisms and altered signaling or expression of PPARG has been associated with decreased insulin action, obesity, dyslipidemia, as well as cardiovascular disease and cancer." (PMID 26606528, 2015). "Diabetes is a serious complication of obesity, which has been associated with metabolic disturbances such as increased insulin, free fatty acids and glycerol." (PMID 26569331, 2015). "Obesity, abdominal obesity in particular, has been associated with the production of adipokines in fat tissues, which, in turn, causes insulin insensitivity in peripheral tissues." (PMID 26284121, 2015). "We also studied the association between circulating ECs and markers of obesity and insulin and glucose homeostasis pre- and postoperatively." (PMID 25874237, 2015). "That obesity associated with a lesser excursion perhaps similarly reflects greater preservation of the capacity for insulin secretion." (PMID 25855488, 2015). "Second, obesity, especially when associated with metabolic syndrome, presents increased levels of insulin and insulin-like growth factor, hormones with potent mitogenic activity toward epithelial cells." (PMID 26684197, 2015). "Obesity was associated with decreases in both insulin sensitivity (Si) and HDL cholesterol concentrations, and increases in TG concentrations." (PMID 26633899, 2015). "Microvascular recruitment was a mediator in the association between obesity and insulin sensitivity." (PMID 26003324, 2015). "The hyperinsulinemia of obesity is a function of both increased pancreatic insulin secretion and decreased insulin clearance, and contributes to cardiovascular risk." (PMID 26297500, 2015). "The major obesity related co-morbidities are impaired glucose tolerance, decreased insulin sensitivity, and dyslipidemia—all being risk factors for cardiovascular diseases." (PMID 26266945, 2015). "These obesity measures were positively associated with indices of glycaemia, and inversely associated with insulin sensitivity." (PMID 25849815, 2015). "Not surprisingly, in our study, we found that circulating PAI-1 levels were associated with obesity, dyslipidemia, and insulin secretion in both genders." (PMID 26633970, 2015). "Higher level of insulin signaling induced fat differentiation, which induced obesity and steatosis in GADD34-deficient mice." (PMID 26316333, 2015). "All the investigated measures of obesity were positively associated with indicators of glycaemia and inversely associated with indicators of insulin sensitivity." (PMID 25849815, 2015). "The major risk factors for NAFLD are obesity, dyslipidemia, and insulin insensitivity, which have been shown to be improved by FGF21." (PMID 26441837, 2015).
Obesity (continued). "Nevertheless, PDZ-RhoGEF has a prominent function in modulating insulin signaling in mouse adipose tissue, with profound effects on whole body physiology, including development of obesity and obesity-associated T2D." (PMID 26512886, 2015). "Of note, in BRS-3 knockout (KO) mice, this receptor has been implicated in insulin release, as well as in the development of metabolic defects and obesity." (PMID 25653074, 2015). "We also examined the associations of NEFA species with overweight/obesity, body fat distribution and insulin sensitivity." (PMID 26011768, 2015). "A shift toward mitochondrial fission with reduction of fusion protein, mainly mitofusin 2, has been associated with reduced insulin sensitivity and inflammation in obesity and IR development." (PMID 26834644, 2015). "This pro-inflammatory protein leads to an increased inflammatory level -also called a chronic low-grade inflammation- which seems to be strictly associated with obesity and insulin signaling impairment." (PMID 26288661, 2015). "In contrast, PTENhaploinsufficiency seen in Cowden syndrome, a cancer predisposition syndrome, isassociated with obesity and paradoxical enhancement of insulin sensitivity." (PMID 25777795, 2015). "CD47 deficient mice challenged with a HF diet had several protective phenotypes as previously observed in TSP1 deficient mice including decreased obesity-associated inflammation and improved glucose tolerance and insulin sensitivity." (PMID 25747123, 2015). "This phenomenon was associated with increased insulin sensitivity in animals induced to obesity by a high fat diet." (PMID 26288661, 2015). "The involvement of B cells in obesity-associated metabolic dysfunction is also supported by the increased insulin sensitivity found in B-cell-deficient mice on HFD compared with wild-type controls." (PMID 26161548, 2015). "While a number of factors likely contribute to the increased cancer risk and cancer-related mortality that accompanies obesity, dysregulated insulin and IGF signaling is thought to play a significant role." (PMID 26029167, 2015). "Increased expression of ECM components in adipose tissue has been repeatedly reported in murine models of obesity and in obese subjects associated with either body mass index (BMI), insulin sensitivity and/or resistance, and/or inflammation." (PMID 26035864, 2015). "The role of the NLRP3 inflammasome in the pathogenesis of obesity-induced insulin resistance is derived from observations that NLRP3 deficient mice fed a high fat diet are more insulin sensitive than HF-diet fed wild-type mice." (PMID 26437377, 2015). "Alterations in autophagy flux can cause defects in insulin signaling and ER stress in peripheral tissues that contribute to obesity." (PMID 25786112, 2015). "This study aimed to explore the molecular basis underlying the impairment in insulin stimulated glucose disposal observed in obesity." (PMID 25876175, 2015). "Diminished obesity-associated insulin action is characterized by chronic inflammation involving infiltration of macrophages and both T and B cells into adipose tissue." (PMID 26606528, 2015). "Although the etiology of NAFLD has not yet been clarified, it is epidemiologically strongly associated with obesity and dysregulated insulin activity in the liver." (PMID 26438035, 2015). "A previous study demonstrated that when obese mice lost weight, benefits of weight loss to improve glucose and insulin tolerance were diminished in mice exposed to PCB-77 during the weight-gain phase of diet-induced obesity." (PMID 25734695, 2015). "We conclude that apoC-III proteoforms are associated with obesity and insulin signaling with apoC-III2 showing a different pattern of association." (PMID 26633899, 2015). "The loss of insulin action is associated with the production of pro-inflammatory biomolecules in obesity conditions." (PMID 26288661, 2015).
Obesity (continued). "and Ruminococcus gnavus, were positively associated with obesity and metabolic traits including body fat increase on a HF/HS diet, insulin levels, and HOMA-IR (P < 0.001)." (PMID 26260972, 2015). "While the cause of low GnRH release in obese patients is unclear, insulin and leptin resistance develops in some neuronal circuits during obesity in a manner similar to insulin resistance in peripheral tissues." (PMID 25946091, 2015). "HFD can induce obesity, which associated with hyperglycemia, hyperlipemia and impaired insulin sensitivity." (PMID 25747866, 2015). "Circulating insulin levels are intimately related to systemic insulin responsiveness, and the most widely held paradigm posits that obesity leads to insulin resistance, causing a compensatory rise in insulin to prevent hyperglycaemia." (PMID 26155745, 2015). "In girls, PAI-1 was positively associated with obesity, hypertriglyceridemia, and insulin secretion." (PMID 26633970, 2015). "Recently, a possible interaction between leptin and insulin, and obesity-related markers of inflammation has been linked to breast cancer outcomes." (PMID 26284121, 2015). "Numerous studies have suggested that moderate regular aerobic exercise can lead to weight loss, fat mass loss, and improved insulin sensitivity in obesity." (PMID 26175963, 2015). "Another mechanism is that inflammatory events decrease the sensitivity to insulin in obese patients, with the focuses on adipose tissue macrophages as the main source of obesity-associated inflammation." (PMID 27525252, 2015). "Adiponectin is the most well-characterised member of the CTRP family, is tightly linked to IR and insulin sensitivity, and is an important biomarker and therapeutic target in obesity-associated metabolic diseases." (PMID 25878729, 2015). "The metabolic effects of apelin described in different mouse models (diet-induced obesity, transgenic models) have underlined the beneficial roles of apelin on both energy metabolism and insulin sensitivity." (PMID 25914650, 2015). "Given that insulin/IGF signaling is known to contribute to obesity-associated cancer, further investigation regarding the efficacy of drugs targeting this system and its downstream effectors in the obese patient population is warranted." (PMID 26029167, 2015). "hNAG-1 increases oxidative metabolism, lower obesity and decrease the insulin/IGF-1 pathway, all of which are associated with survival and longevity." (PMID 25239873, 2014). "Aside from mechanical stress, increased circulating levels of obesity-associated hormones, such as sex steroids, insulin, insulin-like growth factor 1, and leptin, are potential pathogenic mediators in obesity-associated lumbar disc degeneration (LDD)." (PMID 24441571, 2014). "In conditions associated with insulin resistance such as obesity, amylinlevels are often increased in parallel with insulin." (PMID 25191616, 2014). "Overall, systemic oxidative stress-associated obesity directly impacts insulin sensitivity of metabolic organs, promotes inflammation, and alters lipid metabolism or endothelial dysfunction." (PMID 25143800, 2014). "A growing number of studies suggested that adiponectin is decreased in obesity and negatively correlated to visceral fat mass, inflammation, heart disease, injury, and many other diseases but positively to insulin sensitivity and promotes weight loss." (PMID 24899788, 2014). "Using only salivary CRP and insulin as predictors, the overall diagnostic sensitivity for identifying obesity by biomarker status was 89% and specificity was 61%." (PMID 24915044, 2014). "As obesity, visceral adiposity, and hepatic steatosis have been shown to associate with impaired glucose and insulin homeostasis, we subjected the mice to 6 h fasted O-GTT after six weeks of feeding." (PMID 25390887, 2014).